TBR1 (T-box brain transcription factor 1)
Diseases named in the same sentence as TBR1 in open-access papers (continued):
Sharing a sentence is not in itself a finding about the gene and the disease.
Anxiety (8 papers, 2015 to 2025). Intense feelings of nervousness, tension, or panic often arise in response to interpersonal stresses. "Next, we examined other ASD-associated behaviours such as heightened anxiety traits and excessive grooming in Tbr1+/− mice." (PMID 35303947, 2022). "In addition, layer 6-specific deletion of TBR1 leads to the loss of excitatory and inhibitory synapses in layer 6 pyramidal neurons, and anxiety-like and aggressive behaviors." (PMID 31680851, 2019). "In the elevated plus-maze test, Tbr1+/K228E mice spent more time in closed arms, but less time in open arms, indicative of anxiety-like behavior." (PMID 31680851, 2019). "Taken together, these results suggest that Tbr1+/K228E mice display social deficits, repetitive behaviors, altered anxiety-like behavior, and modestly increased locomotion." (PMID 31680851, 2019). "Behaviorally, Tbr1+/K228E mice showed decreased social interaction, increased self-grooming, and modestly increased anxiety-like behaviors." (PMID 31680851, 2019). "Tbr1+/K228E mice showed abnormal behaviors in social, repetitive behavioral, anxiety, and locomotor domains." (PMID 31680851, 2019). "In addition, Tbr1+/K228E mice spent less time in the light chamber in the light-dark test, further indicative of anxiety-like behavior." (PMID 31680851, 2019). "Finally, given that ASD is associated with anxiety and attention-deficit/hyperactivity disorder (ADHD)-like hyperactivity, we measured anxiety-like and locomotor behaviors in Tbr1+/K228E mice." (PMID 31680851, 2019). "In addition, Tbr1+/K228E mice showed increased anxiety-like behavior (elevated plus-maze and light-dark tests) and modestly increased locomotor activity (Laboras test)." (PMID 31680851, 2019). "Thus, long-term 1/4 cocktail treatment improves the social deficits caused by Tbr1 haploinsufficiency without noticeable side effects on body weight, locomotion or anxiety." (PMID 41329641, 2025). "However, Tbr1+/K228E mice also showed reduced habituation to the novel open-field environment, which is known to involve anxiety and may contribute to the increased time spent in the center region of the open-field arena." (PMID 31680851, 2019). "Consequently, the decrease in the number of Tbr1+ cells in juvenile mice may contribute to the abnormal distribution and expression of excitatory and inhibitory neurons in the brain, potentially leading to anxiety and cognitive impairments." (PMID 40248263, 2025). "Similar studies have shown that a decrease in Tbr1+ cells in the mouse PFC can also affect the number of excitatory and inhibitory synapses, disrupting the E/I balance and leading to anxiety-like behavior in mice." (PMID 40248263, 2025). "CQ rescues social interaction in Shank2−/− and Tbr1+/− mice, but it fails to rescue social novelty recognition, repetitive behaviour, hyperactivity or anxiety-like behaviour in Shank2−/− mice." (PMID 25981743, 2015). "Tbr1 haploinsufficiency did not induce excessive grooming nor elevate anxiety in mice." (PMID 35303947, 2022). "Zinc mobilization has also been shown to restore glutamatergic synaptic transmission in the amygdala of Tbr1−/− ASD mice and in the hippocampus of Shank2−/− mice that was accompanied by a significant improvement in social interaction, but not anxiety behaviors, in both ASD mice models." (PMID 30405356, 2018).
schizophrenia (7 papers, 2015 to 2023). A major psychotic disorder characterized by abnormalities in the perception or expression of reality. "The loss of TBR1 expression from the upper cortical layers was documented in all the three schizophrenia organoids, as compared to three controls." (PMID 30446636, 2017). "TBR1 pioneer neurons and reelin, which guides cortico-petal migration, were restricted from the schizophrenia cortex." (PMID 30446636, 2017). "In addition, the Tbr1+/K228E transcriptome was enriched for gene sets associated with bipolar disorder and schizophrenia, but not for gene sets associated with other brain disorders." (PMID 31680851, 2019). "Moreover, the expression levels of TBR1 are increased in patients that suffer from schizophrenia." (PMID 26578866, 2015). "In contrast, in schizophrenia organoids, TBR1+ cells were absent from the upper cortical region, while cells expressing high levels of TBR1 were found concentrated predominantly in the cortical plate and IZ." (PMID 30446636, 2017).
developmental delay (4 papers, 2018 to 2025). "One study describes a patient with a frameshift TBR1 variant who presented with multiple focal epileptic discharges on both awake and sleep EEG, in addition to seizures, ASD, ID, and global developmental delay." (PMID 40004448, 2025). "We also show evidence for a novel interaction between TBR1 and BCL11A, a regulatory protein implicated in a neurodevelopmental syndrome characterized by developmental delay, ID and language deficits." (PMID 30250039, 2018). "Developmental disorders caused by mutations in GATAD2B (OMIM 615074), ADNP (OMIM 615873), BCOR (OMIM 300166) and NR2F1 (OMIM 615722) have features that overlap with those of TBR1-related disorder, including developmental delay, ID, speech and language impairments and autistic behaviors." (PMID 36579832, 2023).
epilepsy (4 papers, 2016 to 2025). A brain disorder characterized by episodes of abnormally increased neuronal discharge resulting in transient episodes of sensory or motor neurological dysfunction, or psychic dysfunction. "In some patients harboring pathogenic TBR1 variants, structural brain abnormalities, neurological features (hypotonia, fine motor delay, abnormal movements, and epilepsy), and skeletal anomalies were also reported." (PMID 40004448, 2025). "It has been suggested that CASK may act via its interaction with Tbr1 (Hsueh, Wang, Yang, & Sheng, 2000), but in a murine model, disruption of the CASK‐Tbr1 interaction did not produce any structural defects or epilepsy." (PMID 32696595, 2020).
Hypoglycemia (3 papers, 2023 to 2025). A decreased concentration of glucose in the blood. "Significant differences in TBR1 were observed (p < 0.02), with the highest percentage of level 1 of hypoglycemia detected at 72 h after the start of the camp and maintained until the end of the camp." (PMID 39064653, 2024). "Regarding time in hypoglycemia, in our series, TBR1 (<4%) and TBR2 (<1%) targets were already being met according to consensus at baseline before the change of system." (PMID 37337407, 2023). "Specifically, both TAR1 (181-250 mg/dl), representing moderate hyperglycemia, and TBR1 (54-69 mg/dl), indicating moderate hypoglycemia, showed negative correlations with the GRI." (PMID 40978913, 2025).
ZIKV infection (3 papers, 2018 to 2020). "Our pipeline provided unbiased quantification of cell population decreases upon Zika virus infection and discovered previously unreported reductions in ventricle volume, ventricle frequency, and a significant change in the spatial context of rare TBR1+ cells." (PMID 33293587, 2020). "Furthermore, at E17.5, we found that both the immature neurons (marked by Tbr1) and mature neurons (marked by NeuN) are depleted upon ZIKV infection." (PMID 31086212, 2019).
glioblastoma (2 papers, 2020 to 2025). The most malignant astrocytic tumor (WHO grade IV). "So, copy number variations for TBR1 have been reported for glioblastomas and mutation of the TBR1 gene was found in medulloblastomas, an embryonic cancer of the brain." (PMID 32070431, 2020). "The up-regulation of TBR1 (9.66), a transcription factor involved in neuronal development, suggests that curcumin may influence differentiation pathways—which is highly relevant in glioblastoma, where differentiation is often impaired." (PMID 40430278, 2025).
microcephaly (2 papers, 2015 to 2019). A congenital or acquired developmental disorder in which the circumference of the head is smaller than normal for the person's age and sex. "Loss of Plzf resulted in microcephaly with thinner cortex and reduced numbers of Tbr1+ neurons in layer VI but not in other layers." (PMID 31027502, 2019). "Microcephaly is also a reported, plausibly due to the functional link between TBR1 and ASPM, a robust candidate for microcephaly, and candidate for positive selection in human lineage." (PMID 26136701, 2015).
renal cell carcinoma (2 papers, 2020 to 2022). "Moreover, Methylation of TBR1 is associated with the progression of renal cell carcinoma." (PMID 36536378, 2022). "We further compared methylation of the TBR1 locus in a subset of 135 primary tumor tissues clinically diagnosed to be free both of lymph node and distant metastasis and 202 cancer metastatic tissues isolated from 105 renal cell cancer patients suffering from metastatic disease." (PMID 32070431, 2020).
viral infection (2 papers, 2020). "Since viral infection produced a ~ 90% decrease in TBR1+ cells, only rare VZs (1–2 per organoid) displayed a thin layer of TBR1 cells in Zika-infected organoids." (PMID 33293587, 2020). "Importantly, at both 2- and 6-month time points following viral infection, the NeuroD1-converted neurons showed immunoactivity for Tbr1 signal, suggesting that NeuroD1-based gene therapy can regenerate cortical neurons in the monkey cortex after ischemic injury." (PMID 33224952, 2020).
Arthritis (1 paper, 2013). Inflammation of a joint. "The Tbr1 null expression data also showed enrichment in two out of the four arthritis-associated gene sets." (PMID 24245670, 2013).
brain malformations (1 paper, 2022). "Accordingly, not only TBR1 loss-of-function but also abnormally increased TBR1 expression could potentially provoke brain malformations and functional deficits." (PMID 35781633, 2022).
dyslexia (1 paper, 2015). A learning disorder characterized by an impairment in processing written words. "Changes in the expression of these ASD- and dyslexia-associated genes provide support for the influence of TBR1 in ASDs." (PMID 26578866, 2015).
dystroglycanopathy (1 paper, 2024). "To compare cortical migration across our five models of dystroglycanopathy, we performed immunostaining for the upper layer marker Cux1 (layers II/III-IV) and the deep layer marker Tbr1 (layers III, VI) in P30 somatosensory cortex." (PMID 38179984, 2024).
ganglioglioma (1 paper, 2018). A well differentiated, slow growing neuroepithelial neoplasm composed of neoplastic, mature ganglion cells and neoplastic glial cells. "In ganglioglioma controls, Tbr1 nuclear labelling of dysmorphic neurons was noted in one case; a variable proportion also showed cytoplasmic OTX1 positive labelling but more consistent labelling was observed with SOX2." (PMID 28833756, 2018). "In Case 8 with the ganglioglioma component, dysplastic neurons were negative with TBR1." (PMID 28833756, 2018).
hemimegalencephaly (1 paper, 2016). "Abnormal distribution of Tbr1+ cells throughout the cortex has been reported in both FCD and hemimegalencephaly, and localization of Tbr1+ cells in the superficial cortical region has been observed in FCD type II cases." (PMID 27042238, 2016).
ischemia (1 paper, 2025). A hypoperfusion of the BLOOD through an organ or tissue caused by a PATHOLOGIC CONSTRICTION or obstruction of its BLOOD VESSELS, or an absence of BLOOD CIRCULATION. "However, reduced brain weight and delayed gyrification on fetal MRI in CHD53 and reduced doublecortin+ neuroblasts, cortical growth, and NeuN/calretinin+ interneurons, but not NeuN/Tbr1+ neurons, in models of perinatal ischemia, support an additional developmental neuronal‐migratory defect." (PMID 40299318, 2025).
language disorder (1 paper, 2018). A category of disorders characterized by an impairment in the development of an individual's language capabilities, which is in contrast to his/her non-verbal intellect. "We found that the TBR1 variants abolished interactions with the FOXP1 and FOXP2 transcription factors involved in ID and severe speech/language disorder, respectively." (PMID 30250039, 2018).
lung carcinoma (1 paper, 2022). "For the two remaining genes, NLGN4Y (ENSP00000342535) and TBR1 (ENSP00000374205), in 2019, researchers from University of Southampton summarized NLGN4Y as a multi-omics level driver for lung cancer at least at epigenomics and transcriptomics levels." (PMID 35155435, 2022).
meningioma (1 paper, 2022). A generally slow growing tumor attached to the dura mater. "Candidates such as DOK7 (3 hits, NC), the PCDH clusters (32 hits, PC), PAX6 (15 hits, PC), and TBR1 (6 hits, PC), among others with dynamic and island-restricted CpGs, constitute potential proliferative biomarkers in meningiomas." (PMID 36551712, 2022).
Obesity (1 paper, 2020). Accumulation of substantial excess body fat. "Of note, comparison of normal and obesity-related tissue sample subsets suggested adiposity as an additional epidemiologic factor for higher TBR1 methylation in normal renal tissues." (PMID 32070431, 2020).
oral cancers (1 paper, 2024). "This analysis revealed that in addition to the positive control GAPDH, all oral cancers (except SCC4) upregulated the miR-155 downstream targets OLFML3, TBR1, BACH1, ZNF652, IRF2-BP2, and ZIC3." (PMID 38396844, 2024).
prostate carcinoma (1 paper, 2020). A carcinoma that arises from epithelial cells of the prostate gland. "Therefore, our results give additional evidence that TBR1 alterations play also a role in human cancers, in particular when considering that 11 out 12 cancer models representing the 3 urological tumor entities of kidney, urothelial, and prostate cancer show high TBR1 methylation." (PMID 32070431, 2020).
renal carcinoma (1 paper, 2020). A carcinoma arising from the epithelium of the renal parenchyma or the renal pelvis. "As our study provided statistical evidence which is in line with a possible contribution of TBR1 alterations in the development and progression of RCC, functional studies are required to clarify the causal relevance of TBR1 alterations for renal cancers." (PMID 32070431, 2020).
neurodevelopmental disorder (6 papers, 2015 to 2025). A behavioral and cognitive disorder with onset during the developmental period that involves impaired or aberrant development of intellectual, motor, or social functions. "TBR1 has been previously implicated in neurodevelopmental disorders, including ASD and ID." (PMID 40956618, 2025). "Our findings enhance understanding of molecular functions of TBR1, as well as highlighting the importance of functional testing of variants that emerge from next-generation sequencing, to decipher their contributions to neurodevelopmental disorders like ASD." (PMID 30250039, 2018). "Computational analyses of gene/mRNA regulatory interactions implicate known neurodevelopmental disorder risk genes (CHD8, TCF4, FMRP, BCL11B and TBR1) as regulators of this cascade and reveal pathways through which they may contribute to disease." (PMID 35031607, 2022). "Thus, HAR-01298, which we show regulates TBR1 expression may coordinate patterning of the frontal cortex, the disruption of which can lead to neurodevelopmental disorders." (PMID 31160561, 2019).
tumor (5 papers, 2020 to 2023). "Here, we found that both tumor and metastatic tissues show a specific increase in TBR1 methylation when compared to the respective predecessor tissues." (PMID 32070431, 2020). "We also questioned whether tumor progression and a concurrent gain of TBR1 methylation can be also detected within the group of primary tumors when comparing for the clinical status distant metastasis, stage and grade of tumors." (PMID 32070431, 2020). "To analyze whether the TBR1 candidate locus shows tumor-specific hypermethylation, we measured 175 corresponding tissue pairs of tumor adjacent normal and tumor tissue specimens." (PMID 32070431, 2020). "Therefore, our results statistically support the view that TBR1 methylation promotes the development both of tumor cells as well as of metastatic cells growing out of primary tumor tissues." (PMID 32070431, 2020). "First, tumor heterogeneity for TBR1 epi-alterations could impede the detection of metastasis-positive tissues leading to a decreased statistical power, in particular when considering that only 16% of primary tumors were clinically classified as metastasis positive." (PMID 32070431, 2020). "Biometric analyses of the TCGA KIRC methylation data revealed candidate loci for age-dependent and tumor-specific DNA methylation within the last exon and in a genomic region corresponding to the 3′UTR TBR1 mRNA." (PMID 32070431, 2020). "The data presented in this report elaborate on amino acid residues in LY6K, which may interact with TbR1 to modulate the TGF-β receptor complex in cancer cells and affect the tumor microenvironment." (PMID 37628960, 2023).
cancer (3 papers, 2012 to 2023). A tumor composed of atypical neoplastic, often pleomorphic cells that invade other tissues. "While this manuscript was in progress we were happy to see that LY6K and TbR1 interacted in cancer cells." (PMID 37628960, 2023). "TBR1 alterations have been found primarily in neurological disorders thus far, while information about TBR1 alterations in human cancers is sparse." (PMID 32070431, 2020). "Relative methylation in cell lines as measured by pyrosequencing demonstrated high level methylation of the TBR1 locus in nearly all of the human cancer cell line models." (PMID 32070431, 2020). "In line with thin information about TBR1 alterations occurring in tumors, methylation of the gene has not been reported until now in the context of any human cancer to the best of our knowledge." (PMID 32070431, 2020).
infection (3 papers, 2019 to 2021). The state of being infected such as from the introduction of a foreign agent such as serum, vaccine, antigenic substance or organism. "“Surface-TBR1” profile analysis showed decreased width of SOX2+ cell distribution after infection, consistent with VZ thinning (red arrow)." (PMID 33293587, 2020). "The primer pairs, (Trypanosoma brucei) TBR1/2 and TeRoTat1.2 (T. evansi Rode Trypanozoon antigen type [RoTat] 1.2), detected the infection after 24 hours earlier than MHCT in both experiments." (PMID 31478734, 2019). "Emergence of TBR1 cells in these specific subregions may have been due to lower virus exposure during infection or to faster recovery after the antiviral response." (PMID 33293587, 2020). "Infection phenotype reduced organoid size, ventricle growth, and the expansion of SOX2 and TBR1 cells." (PMID 33293587, 2020). "Furthermore, TBR1/2 primers displayed clear bands at 1 DPI, and TeRoTat1.2 primers showed a faint band at 1 DPI, with an increased band intensity as the infection progressed towards the parasitaemic stage." (PMID 31478734, 2019).
neurological disorders (3 papers, 2017 to 2025). "Neurological disorders have been attributed to homozygous as well heterozygous loss of TBR1 function due to mutations and chromosomal deletions." (PMID 32070431, 2020). "Dysregulation of prefrontal cortical neurogenesis, such as incomplete aggregation and an abundance of newborn neurons, may lead to neurological disorders during brain development, as the downregulation of Tbr1+ neurons can result in neurological disorders." (PMID 40248263, 2025). "Tbr1 is a transcription factor necessary for directing immature neurons to a glutamatergic phenotype, and the downregulation of Tbr1+ neurons in the developing brain could lead to neurological disorders." (PMID 29098009, 2017).